TDRD10 (tudor domain containing 10)
Synonyms: DKFZp434M202
Tractability: No criterion of Open Targets' tractability assessment is met for any kind of drug.
Gene: Protein-coding gene on chromosome 1 (154,502,219 to 154,548,147, forward strand). Ensembl gene ENSG00000163239.
Subcellular location (Human Protein Atlas): Vesicles
Gene Ontology:
Molecular function: protein kinase A regulatory subunit binding; nucleic acid binding; RNA binding
Cellular component: membrane; mitochondrion
Genetic constraint (gnomAD): Loss-of-function variants: 37 observed, 45.86 expected, observed/expected ratio (o/e) 0.81, 90% interval 0.62 to 1.06. The upper end of that interval is the gene's LOEUF score, 1.06, which puts it in group 4 of 6, group 1 being the genes least tolerant of losing a copy. Missense variants: 357 observed, 430.02 expected, observed/expected ratio (o/e) 0.83, 90% interval 0.76 to 0.91. Synonymous variants: 157 observed, 171.08 expected, observed/expected ratio (o/e) 0.92, 90% interval 0.81 to 1.05.
Homologues: Orthologues: macaque TDRD10 (97% identical), chimpanzee TDRD10 (96% identical), pig TDRD10 (74% identical), tropical clawed frog tdrd10 (36% identical), Drosophila melanogaster tud (13% identical), zebrafish tdrkh (13% identical), Drosophila melanogaster papi (9% identical). Paralogues in human: TDRD6 (18% identical), TDRD15 (17% identical), TDRD5 (15% identical), TDRKH (14% identical), TDRD1 (13% identical), TDRD7 (12% identical).
Diseases named in the same sentence as TDRD10 in open-access papers:
TDRD10 is named in the same sentence as 12 diseases in open-access papers, as found by Europe PMC text mining. Sharing a sentence is not in itself a finding about the gene and the disease. The quoted sentences say what the papers report.
breast carcinoma (7 papers, 2019 to 2025). "Three of these, TDRD10, PRAC2 and TMEM132C, contained CpG sites that showed diagnostic and prognostic value in breast cancer, particularly in estrogen-receptor (ER)-positive samples." (PMID 30866861, 2019). "Novel DNA methylation markers were identified, of which cg12374721 (PRAC2), cg18081940 (TDRD10) and cg04475027 (TMEM132C) show promise as diagnostic and prognostic markers in breast cancer as well as other cancer types." (PMID 30866861, 2019). "Sites cg12374721 (PRAC2), cg18081940 (TDRD10) and cg04475027 (TMEM132C) may be effective as diagnostic and prognostic tools not only in breast cancer but also in other cancer types." (PMID 30866861, 2019). "Other genes we replicated have been reported to play a role in breast cancer progression such as HOXD9, TDRD10, SH3PXD2A and TSPAN15, although these studies did not involve DNA methylation data as a prognostic marker." (PMID 39825380, 2025). "Although no direct link between TDRD10 and CRC has been reported, TDRD10 has been identified as a promising diagnostic and prognostic marker for breast cancer and other cancers, meriting further investigation in CRC." (PMID 40893943, 2025). "Furthermore, 3 CpGs located in genes not previously associated with cancer, PRAC2, TDRD10 and TMEM132C, were able to predict breast cancer overall survival, and more particularly survival of ER-positive patients, suggesting their potential as diagnostic and prognostic markers in BC." (PMID 30866861, 2019).
breast tumor (1 paper, 2019). "Unlike PRAC2, genes TDRD10 and TMEM132C are both downregulated in breast tumor tissue when compared to normal tissue." (PMID 30866861, 2019).
kidney clear cell carcinoma (1 paper, 2019). "TDRD10 was downregulated in 46% of cohorts (similar to BC) but was upregulated in kidney clear cell carcinoma and thyroid carcinoma cohorts." (PMID 30866861, 2019).
cancer (4 papers, 2019 to 2025). A tumor composed of atypical neoplastic, often pleomorphic cells that invade other tissues. "Real-time PCR was performed to check the methylation difference of HOXD9, ZNF154, BCL9, TDRD10, and ANKRD53 genes between the cancer cases and controls." (PMID 34452548, 2021). "TDRD10 and DUT expression have both been linked with poor survival in cancer, but have never previously been studied in EC." (PMID 32899298, 2020).
TDRD10 also shares sentences with these, for which no sentence is quoted: gallbladder cancer (1 paper); gastric cancer (1); melanoma (1); pancreatic cancer (1); sarcoma (1); thyroid carcinoma (1); tumor (1); viral infection (1).